ZRANB2 (zinc finger RANBP2-type containing 2)
Description:
Splice factor required for alternative splicing of TRA2B/SFRS10 transcripts. Binds to ssRNA containing the consensus sequence 5'-AGGUAA-3'. May interfere with constitutive 5'-splice site selection.
Synonyms: ZIS; ZNF265; ZIS1; ZIS2
Tractability: PROTAC: ubiquitination databases record sites on it; its protein half-life has been measured.
Gene: Protein-coding gene on chromosome 1 (71,063,251 to 71,081,289, reverse strand). Ensembl gene ENSG00000132485.
Subcellular location: Nucleus
Subcellular location (Human Protein Atlas): Nucleoplasm
Gene Ontology:
Molecular function: protein binding; RNA binding; lipopolysaccharide binding
Biological process: RNA processing
Cellular component: nucleoplasm; nucleus
Genetic constraint (gnomAD): Loss-of-function variants: 13 observed, 39.63 expected, observed/expected ratio (o/e) 0.33, 90% interval 0.21 to 0.52. The upper end of that interval is the gene's LOEUF score, 0.52, which puts it in group 2 of 6, group 1 being the genes least tolerant of losing a copy. Missense variants: 261 observed, 320.74 expected, observed/expected ratio (o/e) 0.81, 90% interval 0.74 to 0.9. Synonymous variants: 119 observed, 107.58 expected, observed/expected ratio (o/e) 1.11, 90% interval 0.95 to 1.29.
Homologues: Orthologues: chimpanzee ZRANB2 (100% identical), rabbit ZRANB2 (99% identical), guinea pig ZRANB2 (98% identical), mouse Zranb2 (97% identical), dog ZRANB2 (94% identical), macaque ZRANB2 (94% identical), pig ZRANB2 (92% identical), tropical clawed frog zranb2 (88% identical), rat Zranb2 (81% identical), zebrafish zranb2 (75% identical), Caenorhabditis elegans Y25C1A.8 (42% identical), Drosophila melanogaster CG3732 (38% identical).
Diseases named in the same sentence as ZRANB2 in open-access papers:
ZRANB2 is named in the same sentence as 14 diseases in open-access papers, as found by Europe PMC text mining. Sharing a sentence is not in itself a finding about the gene and the disease. The quoted sentences say what the papers report.
glioma (10 papers, 2019 to 2025). A benign or malignant brain and spinal cord tumor that arises from glial cells (astrocytes, oligodendrocytes, ependymal cells). "The function of ZRANB2/SNHG20/FOXK1 axis in glioma associated with vasculogenic mimicry formation was analyzed." (PMID 30744670, 2019). "We chose ZRANB2 for further analysis because it is previously shown to be associated with glioma." (PMID 33080570, 2020). "ZRANB2 was also overexpressed in glioma cells and tissue, being a part of the ZRANB2/SNHG20/FOXK1 axis which was essential in regulating the vasculogenic mimicry formation of glioma." (PMID 34482648, 2021). "RBP-ZRANB2 is overexpressed in glioma cells, knockdown of ZRANB2 inhibits the ability of VM formation in glioma cells through SNHG20/FOXK1 pathway." (PMID 33542193, 2021). "In conclusion, our study demonstrates that lncRNA FAM181A-AS1 promotes growth and survival of glioma cells by enhancing ZRANB2 expression via sponging of miR-129-5p." (PMID 33080570, 2020). "Next, we analyzed the role of ZRANB2 in gliomagenesis by performing plasmid overexpression in glioma cell lines and assaying their cell growth and viability." (PMID 33080570, 2020). "The expression of ZRANB2 in glioma tissues of different grades was up-regulated compared with normal brain tissues, and was positively correlated with pathological grade of glioma." (PMID 30744670, 2019). "The expression of ZRANB2 in glioma tissues as well as glioma cell lines U87 and U251 was detected by western blotting." (PMID 30744670, 2019). "ZRANB2 knockdown inhibits the proliferation, migration, invasion and vasculogenic mimicry formation of glioma cells." (PMID 30744670, 2019). "We further analyzed the nascent SNHG20 and half-life of SNHG20 in glioma cells treated with ZRANB2 knockdown and overexpression." (PMID 30744670, 2019). "To further explore the functional role of ZRANB2 in gliomas, we assessed the effects of ZRANB2 knockdown and overexpression on proliferation, migration, invasion and vasculogenic mimicry formation of U87 and U251 cells." (PMID 30744670, 2019). "ZRANB2 shows upregulated expression in glioma in a clinical and cellular level." (PMID 35602293, 2022). "Therefore, our results demonstrate that lncRNA FAM181A-AS1 promotes growth of gliomas by increasing ZRANB2 expression via sponging of miR-129-5p." (PMID 33080570, 2020). "Our study also confirms that ZRANB2 expression is regulated by miR-129-5p in glioma cells." (PMID 33080570, 2020). "ZRANB2/SNHG20/FOXK1 axis plays an important role in regulating vasculogenic mimicry formation of glioma, which might provide new targets of glioma therapy." (PMID 30744670, 2019). "Consequently, ZRANB2 promoted VM formation in glioma cells at least by increasing the stability of SNHG20." (PMID 30744670, 2019). "We further analyze the functional role of ZRANB2 knockdown and overexpression in gliomas." (PMID 30744670, 2019). "ZRANB2 knockdown inhibits the proliferation, migration, invasion and VM of glioma cells." (PMID 30744670, 2019). "Interestingly, as ZRANB2 was found to be overexpressed in ovarian cancer and glioma, it would be interesting to assess, whether this overexpression is associated with resistance to therapy." (PMID 31943118, 2020). "The RNA-binding protein ZRANB2 directly interacts with SNHG20, enhancing its stability and increasing its levels within glioma cells." (PMID 40277941, 2025). "It has been reported that the ZRANB2/SNHG20/FOXK1 axis plays a crucial role in regulating VM formation in the U87 and U251 glioma cell lines." (PMID 40277941, 2025). "SNHG20, which is stabilized by zinc finger RANBP2-type containing 2 (ZRANB2), maintains the stability of forkhead box K1 (FOXK1) mRNA to accelerate glioma progression." (PMID 38886753, 2024). "The expression of ZRANB2, SNHG20 and FOXK1 in glioma were detected by real-time PCR or western blot." (PMID 30744670, 2019).
glioma (continued). "In summary, our study found for the first time that ZRANB2 and SNHG20 are up-regulated in glioma tissues and glioma cells." (PMID 30744670, 2019). "This study first examined the endogenous expression of ZRANB2, SNHG20 and FOXK1 in glioma tissues and U87 and U251 glioma cells, and studied the effects of ZRANB2, SNHG20 and FOXK1 on VM formation in glioma." (PMID 30744670, 2019). "Furthermore, miR-129-5p overexpression or ZRANB2 knockdown reduces proliferation and colony formation of FAM181A-AS1 overexpressing glioma cells." (PMID 33080570, 2020). "This study demonstrated that the ZRANB2/SNHG20/FOXK1 axis played an important role in regulating the expression of VM-related molecules MMP1, MMP9 and VE-Cadherin, and regulated the VM formation of glioma." (PMID 30744670, 2019). "In addition, transfection with SNHG20(+) could rescued the inhibitory effect of ZRANB2(−) on proliferation, migration, invasion and VM of glioma cells, while SNHG20(−) could rescued the promoting effect of ZRANB2(+) similarly." (PMID 30744670, 2019). "Co-transfection of ZRANB2(−) cells with SNHG20(−) could strongly decrease the expression of MMP1, MMP9, VE-Cadherin and strongly inhibit the abilities of proliferation, migration, invasion and VM of glioma cells." (PMID 30744670, 2019). "However, no report of ZRANB2 expression in glioma tissues and cells and involvement in the regulation of VM formation has been reported." (PMID 30744670, 2019).
breast carcinoma (3 papers, 2020 to 2022). "In fact, high protein levels of SYF2 were associated with bad prognosis in breast cancer, and we found that ZRANB2 mRNA levels were up-regulated 5.4 fold (P < 0.002) in a published dataset of non-responding versus responding breast tumors analyzed before chemotherapy using eprirubicin." (PMID 31943118, 2020). "The doxorubicin-induced accumulation of resistant breast cancer cells in the S phase is dependent on ZRANB2 isoform." (PMID 35602293, 2022). "The NTR protein SYF2 was, together with the zinc finger RNA-binding splicing factor ZRANB2, identified as a putative therapeutic target in a small siRNA screen silencing 19 spliceosome proteins that were found overexpressed in doxorubicin-resistant breast cancer cells." (PMID 34065983, 2021). "Altogether, our data identify AS programs controlled by ZRANB2 and SYF2 and converging on ECT2, that participate to breast cancer cell resistance to doxorubicin." (PMID 31943118, 2020). "In the present study, we identify two convergent AS regulatory pathways (ZRANB2 and SYF2 splicing factors converging on ECT2 splicing) that control resistance to Doxo in breast cancer, specifically in ER+ERBB2- tumors (the main subtype of breast cancer)." (PMID 31943118, 2020). "In all three cases, exon inclusion was higher in MCF7-DoxoR versus MCF-7 cells, and was decreased by both ZRANB2 and SYF2 depletion in MCF7-DoxoR cells and in two additional breast cancer cell lines." (PMID 31943118, 2020). "It was furthermore shown that the exon 5 inclusion variant of ECT2 increased tumor growth of doxorubicin-resistant breast cancer cells and resistance to chemotherapy in vivo, suggesting that this AS event contributed to the resistance induced by SYF2 or ZRANB2 overexpression." (PMID 34065983, 2021). "High mRNA levels of ZRANB2 and SYF2 did not associate with bad prognosis in our cohort of breast cancer patients treated with chemotherapy (data not shown)." (PMID 31943118, 2020).
hepatocellular carcinoma (2 papers, 2022 to 2025). A malignant tumor that arises from hepatocytes. "The bioinformatic analysis revealed the close association of ZRANB2 with cancer stage of hepatocellular carcinoma." (PMID 35602293, 2022). "Based on this database, ZRANB2 expression was also associated with stage of hepatocellular carcinoma." (PMID 35602293, 2022). "ZRANB2 knockdown suppressed cell proliferation and enhanced cell apoptosis of hepatocellular carcinoma." (PMID 35602293, 2022). "ZRANB2 was upregulated by 2.11-fold changes in 374 hepatocellular carcinoma tissues compared with 50 normal samples, as revealed by ENCORI database (P = 9.9e − 21)." (PMID 35602293, 2022). "In our study, ZRANB2 was upregulated in hepatocellular carcinoma and its high expression predicts a poor prognosis of patients with this disease." (PMID 35602293, 2022). "We assumed that HLA-DQB1-AS1 regulates hepatocellular carcinoma progression by binding with zinc finger RANBP2-type containing 2 (ZRANB2)." (PMID 35602293, 2022). "In conclusion, HLA-DQB1-AS1 promotes cell proliferation and inhibits apoptosis in hepatocellular carcinoma by the interaction with ZRANB2 protein." (PMID 35602293, 2022). "HLA-DQB1-AS1 promotes cell proliferation and inhibits apoptosis in hepatocellular carcinoma by the interaction with ZRANB2 protein." (PMID 35602293, 2022). "ZRANB2 knockdown reduced number of colonies and increased number of TUNEL-positive cells, which suggested that ZRANB2 acted as an oncogene in hepatocellular carcinoma." (PMID 35602293, 2022). "The positive expression correlation between HLA-DQB1-AS1 and ZRANB2 was found significant in hepatocellular carcinoma adjacent normal tissues, while in hepatocellular carcinoma tissues, the expression correlation is slight." (PMID 35602293, 2022). "We detected ZRANB2 mRNA expression and demonstrated its upregulation in hepatocellular carcinoma cells." (PMID 35602293, 2022). "Its expression is higher in stage III and lower in stage IV than stage I. We revealed the upregulation of ZRANB2 in hepatocellular carcinoma cells and confirmed that ZRANB2 knockdown suppressed cell proliferation and enhanced cell apoptosis of hepatocellular carcinoma." (PMID 35602293, 2022). "Our study not only innovatively demonstrates the oncogenic roles of HLA-DQB1-AS1 and ZRANB2 in hepatocellular carcinoma but also innovatively identifies the interaction between HLA-DQB1-AS1 and ZRANB2 protein, which enriches the molecular mechanism of the pathogenesis of hepatocellular carcinoma." (PMID 35602293, 2022). "ZRANB2 was upregulated in hepatocellular carcinoma at a clinical and cellular level." (PMID 35602293, 2022). "In addition, more experiments are needed to explore the downstream mRNAs and/or signaling pathways of ZRANB2 protein in hepatocellular carcinoma." (PMID 35602293, 2022). "Moreover, ZRANB2 overexpression rescued the anticancer effect of silenced HLA-DQB1-AS1 in hepatocellular carcinoma cells." (PMID 35602293, 2022). "Moreover, ZRANB2 overexpression rescued the anticancer effects of silenced HLA-DQB1-AS1 on proliferation and apoptosis of hepatocellular carcinoma cells, indicating that HLA-DQB1-AS1 exerts its oncogenic role in hepatocellular carcinoma cells by interaction with ZRANB2." (PMID 35602293, 2022).
ovarian carcinoma (2 papers, 2018 to 2020). A malignant neoplasm originating from the surface ovarian epithelium. "As ZRANB2 is upregulated in types of ovarian carcinoma and acts on the alternative splicing of genes implicated in tumor development, we suggest a role for OR4C6 in the development of pancreatic cancer." (PMID 29497600, 2018).
leukemia (1 paper, 2021). A malignant (clonal) hematologic disorder, involving hematopoietic stem cells and characterized by the presence of primitive or atypical myeloid or lymphoid cells in the bone marrow and the blood. "In addition, we identified genes of previously unknown cancer relevance with regards to leukemia circulation (e.g., LRIF1, DNAJC1, and CMC2) and therapeutic treatment (e.g., EBPL, MESDC2, ZRANB2, GTF2A2)." (PMID 34764253, 2021).
serous papillary carcinomas (1 paper, 2020). "Besides, ZRANB2 is highly expressed in the serous papillary carcinomas of the ovaries." (PMID 33080570, 2020).
triple-negative breast carcinoma (1 paper, 2020). An invasive breast carcinoma which is negative for expression of estrogen receptor (ER), progesterone receptor (PR), and human epidermal growth factor receptor 2 (HER2). "Consistently, we found that depletion of the ECT2-Ex5+ isoform (as well as depletion of ZRANB2 or SYF2) did not affect Doxo survival in two triple-negative breast cancer cell lines." (PMID 31943118, 2020).
type 2 diabetes (1 paper, 2019). "One of the candidate genes displaying a 12-h rhythmic FIRMAGene score in BAT was the type 2 diabetes-associated gene Capn10 which encodes for eight known protein isoforms in humans and has been reported as a target of the splicing factor ZRANB2." (PMID 31443305, 2019).
cancer (6 papers, 2020 to 2024). A tumor composed of atypical neoplastic, often pleomorphic cells that invade other tissues. "Heterozygous amplifications and deletions are the main types of copy number variations in molecular VM-related DEGs in pan-cancer, among which the copy numbers of NTN1, SIPR1, LAMTOR5, and ZRANB2 are heterozygous deletions in most tumors." (PMID 37197406, 2023). "The functional group of RNA binding proteins included ELAVL1, ZRANB2 and HNRNPA1, whose role in alternative splicing of transcripts to serve tumour development have made them a focus of recent efforts to target altered RNA splicing in cancer." (PMID 37997254, 2024). "It would be interesting to determine, whether the S-phase accumulation phenotype and the AS regulatory pathways (involving ZRANB2, SYF2 and ECT2-Ex5) that we identified, may be related to the cancer stem cell phenotype of Doxo-resistant cells." (PMID 31943118, 2020).
tumor (6 papers, 2018 to 2024). "ZRANB2(−), SNHG20(−) and ZRANB2(−) + SNHG20(−) group had the smaller tumor size and longer survival time than ZRANB2(−)-NC + SNHG20(−) group." (PMID 30744670, 2019). "In addition, ZRANB2(−) + SNHG20(−) group gained the smallest tumor size and the longest survival time among all the groups." (PMID 30744670, 2019). "Another work described three other tumor genes (CCDC66, ZRANB2 and VCPKMT) for positive margin prediction based on gene expression signature." (PMID 38188288, 2023).
infection (2 papers, 2015 to 2019). The state of being infected such as from the introduction of a foreign agent such as serum, vaccine, antigenic substance or organism. "Several infection-induced SUMO targets also are involved in mRNA maturation events, such as 3′ end pre-mRNA processing (CPSF1, CPSF2, FIP1L1, RBBP6, and WDR33), splicing (CLASRP, SFPQ, and ZRANB2), and nuclear RNA quality control (ZC3H18, ZCCHC7, and PAPD5)." (PMID 26549460, 2015).
ZRANB2 also shares sentences with these, for which no sentence is quoted: breast tumors (1 paper); gram-negative bacterial infections (1); pancreatic cancer (1).